ARHGAP10 (Rho GTPase activating protein 10)
Diseases named in the same sentence as ARHGAP10 in open-access papers (continued):
Sharing a sentence is not in itself a finding about the gene and the disease.
breast carcinoma (continued). "We therefore hypothesized that there was a relationship between the expression of ARHGAP10 and chemotherapy response, and the combination of epirubicin, cyclophosphamide and docetaxel may be less effective in breast cancer patients with low expression of ARHGAP10." (PMID 31396458, 2019). "Therefore, ARHGAP10 in breast cancer remains to be investigated in detail." (PMID 31396458, 2019). "However, miRNAs and other non-coding RNAs that modulate the expression of ARHGAP10 in breast cancer are unknown." (PMID 31396458, 2019). "This suggested that ARHGAP10 could be a predictor of breast cancer prognosis." (PMID 31396458, 2019). "The relationship between ARHGAP10 and RFS was analyzed using Kaplan–Meier Plotter in 3,955 breast cancer cases." (PMID 31396458, 2019). "The IHC staining results, as determined by the product of the proportion of positive staining cells and staining intensity, showed that low expression of ARHGAP10 was more frequent in breast cancer tissues than in non-cancerous tissues (p < 0.001)." (PMID 31396458, 2019).
cognitive deficits (3 papers, 2021 to 2024). "Notably, acute treatment with fasudil rescued the methamphetamine (0.3 mg/kg, i.p.)-induced cognitive impairment in the visual discrimination tasks in Arhgap10 S490P/NHEJ mice." (PMID 37958606, 2023).
acute myeloid leukemia (1 paper, 2019). Acute myeloid leukemia (AML) is a group of neoplasms arising from precursor cells committed to the myeloid cell-line differentiation. "However, we found ARHGAP10 was upregulated in lymphoid neoplasm diffuse large B-cell lymphoma, acute myeloid leukemia and thymoma with the use of GEPIA." (PMID 31396458, 2019).
Anxiety (1 paper, 2020). Intense feelings of nervousness, tension, or panic often arise in response to interpersonal stresses. "For example, anxiety-like behavior in the elevated plus maze test was increased in the Arhgap10 S490P/NHEJ mice compared with their WT litter mates." (PMID 32699248, 2020).
autoimmune encephalitis (1 paper, 2022). Inflammation of the brain secondary to an immune response triggered by the body itself. "Further studies on the clinical and diagnostic implications of ARHGAP10-IgG/anti-Ca2 seropositivity in patients with autoimmune encephalitis are warranted." (PMID 35624318, 2022). "Further studies are warranted to define the frequency, specificity and pathophysiological relevance of ARHGAP10/anti-Ca2 antibodies in larger cohorts of patients with suspected autoimmune encephalitis and controls." (PMID 35624318, 2022). "We demonstrate that a substantial proportion of patients with ARHGAP26-IgG/anti-Ca-positive autoimmune encephalitis co-react with ARHGAP10." (PMID 35624318, 2022). "We found that serum and CSF IgG from ARHGAP26-IgG/anti-Ca-positive patients indeed co-reacts with ARHGAP10 in a substantial proportion of cases, rendering ARHGAP10 a new target antigen in autoimmune encephalitis." (PMID 35624318, 2022). "Here we demonstrate that the majority of ARHGAP26/GRAF-IgG-positive patients with autoimmune encephalitis have antibodies that co-react with ARHGAP10/GRAF2, a protein expressed throughout the CNS." (PMID 35624318, 2022). "Therefore, we hypothesised that cross-reactivity of ARHGAP26-IgG/anti-Ca may render ARHGAP10 an additional immune target in patients with ACA and, possibly, other forms of autoimmune encephalitis associated with ARHGAP26-IgG/anti-Ca seropositivity." (PMID 35624318, 2022).
Autoimmunity (1 paper, 2022). The occurrence of an immune reaction against the organism's own cells or tissues. "Of note, however, ARHGAP10 is also expressed outside of the cerebellum, and autoimmunity to ARHGAP10 may thus explain the occurrence of extracerebellar symptoms in ARHGAP26-IgG/anti-Ca-positive patients." (PMID 35624318, 2022). "Our data suggest that additional autoimmunity to ARHGAP10 might contribute to the pathogenesis of neuroinflammation in a subgroup of ARHGAP26-IgG/anti-Ca-positive patients." (PMID 35624318, 2022).
embryonal carcinoma (1 paper, 2022). A non-seminomatous malignant germ cell tumor characterized by the presence of large germ cells with abundant cytoplasm resembling epithelial cells, geographic necrosis, high mitotic activity, and pseudoglandular and pseudopapillary structures formation. "Mutations in ADAMTS20, ARHGAP10, OR1L4, PDS5A, and RPLP0 were only found in mixed germ cell tumors, while mutations in B3GNT8, CAPN7, FAT4, GRK1, TACC2 and TRAM1L1 were only observed in embryonal carcinoma, and their mutation frequency was around 2%." (PMID 36713456, 2022).
gastric tumors (1 paper, 2023). "However, ARHGAP10 manifested as an oncogene in gastric tumors and non-small cell lung cancer (NSCLC)." (PMID 38041020, 2023).
Headache (1 paper, 2022). Cephalgia, or pain sensed in various parts of the head, not confined to the area of distribution of any nerve. "Moreover, ARHGAP10-IgG was negative in the HC and the headache control subgroup." (PMID 35624318, 2022).
intellectual disabilities (1 paper, 2020). "While ARHGAP10 has not been previously implicated in SCZ, rare CNVs in this gene have been reported in patients with various brain disorders, including generalized seizures, intellectual disabilities, and ventriculomegaly, suggesting its clinical significance." (PMID 32699248, 2020).
mental disorder (1 paper, 2020). A disease that has its basis in the disruption of mental process. "We hypothesized that the coexistence of the ARHGAP10 deletion and the missense variant is associated with the molecular pathogenesis of mental disorders." (PMID 32699248, 2020).
metastasis (1 paper, 2019). The spread or migration of cancer cells from one part of the body (where they first appeared) to another. "However, ARHGAP10 expression was not significantly correlated with age (p = 0.287), tumor size (p = 0.217), ER status (p = 0.366), PR status (p = 0.245), HER2 (p = 0.167), pathological grade (p = 0.379) and lymph node metastasis (p = 0.209)." (PMID 31396458, 2019).
non-small cell lung carcinoma (1 paper, 2021). A group of at least three distinct histological types of lung cancer, including non-small cell squamous cell carcinoma, adenocarcinoma, and large cell carcinoma. "Herein, we investigated the relationship between the trait of ARHGAP10 and non-small cell lung cancer (NSCLC) pathological process." (PMID 34174897, 2021).
orofacial cleft (1 paper, 2022). A disorder of facial skeleton that is characterized by cleft lip and/or cleft palate that result in feeding, speech and hearing problems caused by failures during development. "The protein-truncating DNMs were found in ACTL6A, ARHGAP10, MINK1, TMEM5 and TTN genes, all of which are loci with substantial annotation, functional and/or animal model data supporting their roles in orofacial clefts." (PMID 35817949, 2022).
periodontitis (1 paper, 2022). An acute or chronic inflammatory process that affects the tissues that surround and support the teeth. "During the inflammatory response of periodontitis, the lymphocytes, macrophage and neutrophils are regulated by expression of multiple genes, such as ARHGAP10, ARPC1B, DOCK1, FGF2/4, TNFRSF1B, NXT1, and AHR, all of which were identified in our analysis." (PMID 35491409, 2022).
Ventriculomegaly (1 paper, 2016). An increase in size of the ventricular system of the brain. "Fetus 5, diagnosed with ventriculomegaly, carried a 0.18-Mb deletion involving most of the ARHGAP10 gene on chromosome 4q31.23." (PMID 27087860, 2016).
tumor (10 papers, 2016 to 2025). "CXCL12 decreases the expression of the tumor-suppressor ARHGAP10 through VEGF signaling and promotes EOC cell invasion." (PMID 35269786, 2022). "The protein expression of ARHGAP10 was analyzed in 30 paired tumor tissues and corresponding adjacent normal tissues by IHC." (PMID 31396458, 2019). "Although both cells were able to form tumors, the tumor growth rate of nude mice injected with ARHGAP10-overexpressed cells was significantly more slowly than that of mice injected with control cells." (PMID 27010858, 2016). "ARHGAP10 has been reported to be downregulated in OC tissues and cell lines, It may also serve as a candidate tumor suppressor in other cancers, It played an important antitumor effect in the progression of different cancers through various pathways." (PMID 38230565, 2024). "In these samples, 71% (135/190) of tumor tissues showed low expression of ARHGAP10." (PMID 31396458, 2019). "Therefore, we speculated that SMAD4 plays a tumor suppressive role by upregulating ARHGAP10 expression and further inhibiting the PI3K/AKT/HK2 pathway." (PMID 38230565, 2024). "Therefore, mechanistically, our research elucidated the effect of ARHGAP10 as a tumor suppressor that might inhibit the glycolysis metabolism of OC by inhibiting the PI3K/AKT/HK2 pathway." (PMID 38230565, 2024). "Hence, ARHGAP10 may serve as a tumor suppressor through inactivating Cdc42, as well as inhibiting cell cycle, replication and BER pathways." (PMID 27010858, 2016). "ARHGAP10 showed lower IHC score and p‐AKT showed higher IHC score in tumor tissues compared with normal tissues." (PMID 38230565, 2024). "Other BAR-containing RhoGAPs, such as ARHGAP10 (GRAF2), are tumor-suppressive in nature." (PMID 41301045, 2025). "The tumor-derived exosomes could take part in the NSCLC development, such as circRNA ARHGAP10, circRNA MEMO1, and hsa_circ_0002130." (PMID 35582196, 2022). "Positive log2 (Tumor/Normal) indicated increased expression of ARHGAP10 in tumor tissue while negative log2 indicated reduced expression of ARHGAP10 in tumor tissue." (PMID 27010858, 2016).
cancer (7 papers, 2016 to 2024). A tumor composed of atypical neoplastic, often pleomorphic cells that invade other tissues. "Our data suggest an important role of ARHGAP10 in the molecular etiology of cancer and implicate the potential application of ARHGAP10 in cancer therapy." (PMID 27010858, 2016). "Previous studies have demonstrated the biological function of ARHGAP10 in malignant tumors." (PMID 34174897, 2021). "GSEA results indicate that ARHGAP10 is involved in certain cancer-related signaling pathways." (PMID 31396458, 2019). "Collectively, these findings suggested that ARHGAP10 was involved in different aspects of cancer." (PMID 31396458, 2019). "Emerging evidence showed the critical integration of ARHGAP10 in epithelial–mesenchymal transition (EMT) and metastasis in cancer progression." (PMID 34174897, 2021). "Rho GTPase-activating protein 10 (ARHGAP10), which catalyzes the conversion of active Rho GTPase to the inactive form, is downregulated in some cancers." (PMID 31396458, 2019). "Previous studies of ARHGAP10 in cancer did not examine the relationship between the expression of ARHGAP10 at protein level and clinicopathological parameters, which are important for patient prognosis and therapy options." (PMID 31396458, 2019).
infection (2 papers, 2016 to 2022). The state of being infected such as from the introduction of a foreign agent such as serum, vaccine, antigenic substance or organism. "We ectopically expressed the ARHGAP10 Arf-BD with a GFP tag in HeLa cells for 6 h followed by infection with R. typhi." (PMID 27698019, 2016). "A study has shown that the expression of ARHGAP10 could be related to the infection of Listeria, in which knockdown the expression of ARHGAP10 impaired alpha-catenin recruitment, and then inhibited the invasion of Listeria." (PMID 35491409, 2022).
neurodevelopmental disorder (1 paper, 2020). A behavioral and cognitive disorder with onset during the developmental period that involves impaired or aberrant development of intellectual, motor, or social functions. "Therefore, we next established Case #5 iPSCs to further determine whether ARHGAP10 variants are associated with neurodevelopmental disorders in humans, and compared the in vitro morphological phenotypes related to neurite elongation and maturation between Case #5 and healthy controls." (PMID 32699248, 2020).
ARHGAP10 also shares sentences with these, for which no sentence is quoted: gastric cancer (2 papers); bladder cancer (1); bladder urothelial carcinoma (1); cervical squamous cell carcinoma (1); colon adenocarcinoma (1); colon carcinoma (1); diffuse large B-cell lymphoma (1); endocervical adenocarcinoma (1); esophageal cancer (1); glioblastoma (1); head and neck squamous cell carcinoma (1); invasive breast carcinoma (1); invasive ductal breast carcinoma (1); kidney chromophobe (1); liver cancer (1); lung adenocarcinoma (1); lung squamous cell carcinoma (1); lymph node metastasis (1); lymphoid neoplasm (1); mixed germ cell tumor (1); mood disorder (1); neurological disease (1); osteosarcoma (1); pancreatic cancers (1); prostate adenocarcinoma (1); rectum adenocarcinoma (1); skin cutaneous melanoma (1); testicular germ cell tumor (1); thymoma (1); uterine carcinosarcoma (1).
A further 2 diseases each share a sentence with ARHGAP10 in 1 paper.